RB1 (RB transcriptional corepressor 1)
Diseases named in the same sentence as RB1 in open-access papers (continued):
Sharing a sentence is not in itself a finding about the gene and the disease.
bladder cancer (103 papers, 1995 to 2025). "Several studies have demonstrated that mutations in RB1 are frequently found in bladder cancer, although, as far as we know, the specific mutation (c.13delA; loss-of-function mutation) found in our cohort had not been described before." (PMID 38098507, 2023). "Genetic risk factors associated with bladder cancer include mutations of the retinoblastoma, RB1, gene as well as mutations in PTEN that are also associated with breast and thyroid cancers and Cowden disease." (PMID 33937056, 2021). "Previous studies have demonstrated genomic alterations in CDKN2A in 20 to 60% of bladder carcinomas, which are associated with either RB1 deletions or E2F amplification." (PMID 34885040, 2021). "Mutations in RB1 are associated with sensitivity to the SYK inhibitor BAY-61–3606 in bladder cancer cell lines." (PMID 30526857, 2018). "Because of this reason, it is possible that Rb1 mutation also leads to SLD5 overexpression in bladder cancer cells." (PMID 27499248, 2016). "Rb1 knockout mutations are well studied in bladder cancer, and have been linked to decreased apoptosis, higher T-cell inflammatory responses, and predict worse overall survival in bladder cancer patients." (PMID 40278322, 2025). "In bladder cancer, studies have demonstrated a high prevalence of RB1 gene mutations." (PMID 39779467, 2025). "RB1 mutations were found to be prone to high-grade bladder cancer, astrocytic gliomas, and Merkel cell carcinoma, and they could function by activating the NF-κB pathway and exerting anti-inflammatory effects." (PMID 37020866, 2023). "What is interesting is that the same RB1 is also mutated at a higher percentage in patients with bladder cancer, so there might be an association with the higher increase in both of those cancers specifically for Black individuals." (PMID 36466542, 2022). "Similarly, RB1 is also a cancer-suppressive gene and its mutation is common in bladder cancer samples." (PMID 34122523, 2021). "Choi once reported that bladder cancer with mutation of RB1 and NFE2L2 can be enriched into basal subtype of muscle-invasive bladder cancer, which could be divided into epithelial–basal and more clinically aggressive mesenchymal subtypes." (PMID 34122523, 2021). "Moreover, tumor suppressor gene, Rb1, works as an S phase transition inhibitor is often mutated in bladder cancer patients." (PMID 27499248, 2016). "Moreover, RB1 gene function loss has been found involving mutations in both alleles with retention of heterozygosity at the RB1 locus, as described in bladder carcinomas." (PMID 12556968, 2003). "Since KDM6A connects KMT2D and RB1 mutations we hypothesize that there is a biological pathway that unites the impact of these three mutated genes and is important for the biologic fitness of bladder cancer cells." (PMID 35073341, 2022). "RB1 loss (inclusive of LOF mutations and deep deletions) was seen at similar frequencies in both ERBB2amp and ERBB2mut bladder cancer (21.2% and 25.1%, respectively) and NSCLC (9.7% and 10.5%, respectively) and less frequently in other tumor types." (PMID 40178042, 2025). "At the genomic level, both sets of PDOs harbor common mutations associated with bladder cancer, such as PIK3CA, FGFR3, and RB1." (PMID 39921252, 2025).
bladder cancer (continued). "In bladder cancer, depletion of RB transcriptional corepressor 1 activates the E2F3, Myc, and mTOR signaling pathways to facilitate proliferation and restrain apoptosis of cancer cells." (PMID 34644734, 2021). "It has been established that RB1 status predicts response to cisplatin-based chemotherapy in bladder cancer." (PMID 33216841, 2020). "In contrast to our findings in chondrosarcoma, deletion of RB1 has been described to enhance radiosensitivity in breast, prostate and bladder cancer." (PMID 31160965, 2019). "Two additional genes, CCND1 and RB1, identified in the bladder cancer signaling network are known biomarkers, and the third gene identified in the bladder cancer signaling network (CDK4) is a known inhibitor of bladder cancer." (PMID 29912931, 2018). "Five genes in this network (E2F1, E2F3, EGFR, RAF1, and RB1) significantly overlapped genes in the bladder cancer pathway from the Kyoto Encyclopedia of Genes and Genomes (KEGG) database (FDR q<0.01)." (PMID 29140994, 2017). "Conversely, RB1 mutations were linked to poorer outcomes, as reported in non–small cell lung and bladder cancers." (PMID 40911493, 2025). "We have shown that PEMF upregulates Rb1 in HT-1376 bladder cancer cells too." (PMID 40278322, 2025). "In bladder cancer, ATM/RB1 mutations predicted poorer survival." (PMID 36056635, 2022). "Additionally, the K810 methylation of the tumor suppressor protein RB1 increases the phosphorylation level of adjacent S807/S811, which further enhances the cell cycle progression of bladder cancers." (PMID 30244175, 2018). "Moreover, downregulation of RB1 had been detected in breast and bladder cancer." (PMID 32013999, 2020). "Therefore, the analysis of RB1 status might be useful to select patients with bladder cancer who would benefit from a treatment schedule including radiotherapy, which has been shown to induce ceramide." (PMID 26160835, 2015). "Data identified that in the low HER2 cohort and different ATM levels (high/low); ABL1, SMAD4, RB1 and PARP1 were significantly upregulated and AKT1, AKT2, TSC2, RPTOR and mTOR were significantly downregulated in bladder cancer." (PMID 36056635, 2022).
bladder cancer (continued). "A total of nine chr3p25 and chr11p11 genes were functionally connected to genes in the KEGG bladder cancer pathway (E2F1, E2F3, EGFR, RAF1, RB1) or to other cancer-related genes (AKT2, PIK3CA, RB1, TRIO)." (PMID 29140994, 2017). "Accordingly, three bladder cancer cell lines (T24, 5637, and HT1376) representative of two distinct carcinogenesis pathways to invasive cancer (FGFR3/CCND1 and E2F3/RB1) were used." (PMID 27835695, 2016). "Three of the most studied bladder cancer cell lines (T24, 5637, and HT1376), reflecting different molecular pathways for cell invasion (FGFR3/CCND1and E2F3/RB1), were chosen envisaging the identification of a ubiquitous reference gene." (PMID 27835695, 2016). "We have selected three bladder cancer cell lines (T24, 5637, and HT1376), representative of two distinct molecular pathways to invasive cancer (FGFR3/CCND1and E2F3/RB1), and widely explored by us in the establishment of novel therapeutic schemes." (PMID 27835695, 2016). "An anti-correlation of RB1 and CDKN2A expression was also reported in SCLC, gastric cancer, oral cavity squamous carcinoma or urinary bladder cancer." (PMID 21447152, 2011). "Similarly, circRNA RB1-ITM2B originates from a read-through transcript of the tumour suppressor RB1 gene into the downstream ITM2B as detected in melanoma, lung and bladder cancers." (PMID 39321865, 2025). "RB1 is a prognostic candidate for immunotherapy, as decreased expression of RB1 in hepatoma or bladder cancer has been correlated with a lack of immune response." (PMID 37441425, 2023). "Yet, there are currently no larger datasets analyzing RB1 phosphorylation status in bladder cancer." (PMID 30258198, 2018). "Conversely, RB1 altered expression seems to be predictive of nonresponse to intravesical bacille Calmette-Guerin (BCG) +/− IFN-α treatment and tumor recurrence in bladder cancer patients." (PMID 26160835, 2015). "Therefore, it is necessary to explore the correlation of miRNA and Rb1 with the occurrence and development of bladder cancer after SCI as the path of pure bladder cancer related molecules may not be appropriate for bladder cancer patients after SCI." (PMID 38778291, 2024).
ovarian carcinoma (80 papers, 2007 to 2025). A malignant neoplasm originating from the surface ovarian epithelium. "Although subclonal RB1 loss seems to be rare in ovarian carcinoma (0.89%), the relevance of subclonal RB1 loss should be studied in the future using full-faced tumor sections, and ideally paired primary and relapse specimens to assess clonality over time." (PMID 38837893, 2024). "Previous evidence showed that high expression of RB1 is associated with a poor prognosis in advanced-stage ovarian carcinoma patients." (PMID 38612869, 2024). "Globally, 2 down- and 8 upregulated genes are confirmed to be significant by the system, thus stressing the importance of these mRNAs to discriminate signatures of RB1 loss in Ovarian carcinoma." (PMID 30813319, 2019). "In this study, we sought to evaluate the association of HR pathway mutations, HR deficiency scores and CCNE1 and RB1 CNA with response to platinum retreatment in ovarian cancer patients in the platinum-resistant setting." (PMID 31060523, 2019). "(2013) studied plasma DNA in ovarian cancer patients who received cisplatin therapy and found a noticeable increase in RB1 mutation in these patients." (PMID 29797793, 2018). "We characterized an ovarian cancer derived variant of RB1 that possesses biochemical properties that are comparable to our previously published Rb1ΔL mutant allele." (PMID 20298605, 2010). "We assessed tumor samples from a cohort of more than 7,000 patients with ovarian carcinoma, including a subset with high-resolution genomic data, to understand how RB1 loss may impact therapeutic response and patient survival." (PMID 38837893, 2024). "However, high expression of RB1 is associated with poor prognosis in advanced-stage ovarian carcinoma patients." (PMID 35299734, 2022). "Interestingly, the mutation rates for commonly reported genes in ovarian cancer such as RB1, PTEN, PIK3CA, NRAS, KRAS, and BRAF were below 3% in the entire cohort." (PMID 33016563, 2021). "The retinoblastoma protein (pRB) can promote HR and NHEJ, RB1 loss is linked to increased DNA damage, and the combination of HR gene and RB1 mutations is beneficial in ovarian cancer, but whether directly targeting these repair processes could enhance RB treatment is unclear." (PMID 32572160, 2020). "RB1 protein expression was classified by immunohistochemistry in ovarian carcinomas of 7,436 patients from the Ovarian Tumor Tissue Analysis consortium." (PMID 38837893, 2024). "The CDK2/4/6, cyclin D1/E1 and RB1/pRB1 protein expression were investigated in 300 ovarian cancers and correlated with clinicopathological parameters and patient outcomes." (PMID 38612869, 2024). "In the current study, we have comprehensively investigated the sub-cellular localisation and clinicopathological significance of cyclins D1/E1, CDK2/4/6 and RB1/pRB1 in a cohort of clinical ovarian cancers." (PMID 38612869, 2024). "RB1 protein expression was assessed by IHC in tumor samples from 7,436 patients with ovarian carcinoma using TMAs from 20 centers participating in the OTTA consortium." (PMID 38837893, 2024).
ovarian carcinoma (continued). "The purpose of this study was to evaluate RB1 expression and survival across ovarian carcinoma histotypes and how co-occurrence of BRCA1 or BRCA2 (BRCA) alterations and RB1 loss influences survival in tubo-ovarian high-grade serous carcinoma (HGSC)." (PMID 38837893, 2024). "This evidence strongly illustrates the potential of RB1 as an immune and prognostic marker in ovarian cancer." (PMID 35735060, 2022). "Our analysis revealed differential regulation of RBAK and RB1 in patients, which implies the importance of interactions between these two genes in ovarian cancer and their potential as drug targets." (PMID 35735060, 2022). "For this aim, they screened 40 ovarian cancer cell lines for their sensitivity to palbociclib and identified the so-called Rb1-proficient cell lines, with low p16INK4A and CCNE1 expression, as the most responsive to CDK4/6i." (PMID 34204543, 2021). "We exploited a public transcriptomic dataset (GSE76689), a silencing experiment designed to dissect the role of RB1 in Ovarian carcinoma." (PMID 30813319, 2019). "MYC and RB1 had the highest frequency of copy number variations (6/21, 29%) in recurrent ovarian cancers, followed by PIK3CA (3/21, 14%)." (PMID 29797793, 2018). "In drug‐resistant recurrent ovarian cancer patients, RB1 had the highest frequency of copy number variations (4/10, 40%), which was followed by MYC (3/10, 30%)." (PMID 29797793, 2018). "We found that in drug‐resistant recurrent ovarian cancer patients, RB1 had the highest frequency of copy number variations (40%)." (PMID 29797793, 2018). "MYC had the highest frequency of copy number variations (6/21, 29%) in recurrent ovarian cancer patients, followed by RB1 (6/21, 29%) and PIK3CA (3/21, 14%)." (PMID 29797793, 2018). "The TCGA group has identified several pathways that are commonly altered in ovarian cancer, including the RB1 signalling pathway, PI3K/RAS signalling pathway, FOXM1 transcription factor network and HR pathways." (PMID 29116111, 2017). "We have also shown the differential effects of Rb1 and compound K in ovarian cancer and normal human ovarian surface epithelial cells." (PMID 27825116, 2017). "Rb1 and compound K treatment also inhibited the self-renewal of CSCs derived from ovarian carcinoma patients as well as in xenograft tumor model." (PMID 27825116, 2017). "RB1 is a significantly genetic alteration gene, and the RB pathway is regulated in 67% of ovarian cancer cases." (PMID 26735889, 2016). "The RB1 gene is only existed in the module of ovarian cancer subtype 2, and the main difference between the two subtypes is found in the RB pathway." (PMID 26735889, 2016). "In summary, cyclin E1 signaling confers resistance to PD0332991 in RB1-proficient ovarian cancer cells." (PMID 25557169, 2015). "This PM has two genes (RB1 and CCNE1) in the well-characterized RB1 cancer pathway that plays important roles in ovarian cancer tumorigenesis." (PMID 26317392, 2015).